ICAM1 (intercellular adhesion molecule 1)
Diseases named in the same sentence as ICAM1 in open-access papers (continued):
Sharing a sentence is not in itself a finding about the gene and the disease.
infertile (5 papers, 2012 to 2025). "The single nucleotide polymorphism ICAM-1 rs5498 (1462A>G) is linked to an increased incidence of obstructive azoospermia, with a considerably greater prevalence of AG heterozygotes among infertile males." (PMID 36071829, 2022). "The present study emphasized the association of lifestyle habit with the ICAM1 and HLA-G genes expression alteration and oocyte quality as an opinion for the deeper understanding of the etiology of infertile women with POR patients." (PMID 33953208, 2021). "This suggests a feedback loop where IL6-induced inflammation upregulates ICAM1, while miR-146a-5p acts as a compensatory brake, a mechanism likely disrupted in infertility." (PMID 41227338, 2025). "In this study, we evaluated the expression profile for ICAM-1 and HLA-G genes in the cumulus cells of infertile women with poor response to ovarian stimulation (POR) based on their healthy lifestyle habit." (PMID 33953208, 2021). "Decreased production of ICAM-1 by PBMCs of infertile women with ASA as compared to healthy controls is of particular interest, suggesting more complex interplay of factors involved in diapedesis." (PMID 22952917, 2012). "Our findings revealed that a major contributor to oocyte maturity disorder and infertility in the POR patients without a healthy lifestyle habit can be a reduction in ICAM1 and HLA-G transcript and proteins expression as well as hypermethylation of DNA in ICAM1 and HLA-G." (PMID 33953208, 2021).
latent infection (5 papers, 2013 to 2024). "ICAM-1 interaction with leukocyte function-associated antigen (LFA)-1 can facilitate induction of latent infection in the DC-T-cell model, while in other models of in vitro latency CD2 expression, a molecule that binds to LFA-3, was increased on latently infected cells." (PMID 26362311, 2015). "While others have shown that low levels of the KSHV protein K5 can still down-regulate ICAM1 expression, we believe it is likely that during latent infection, the inhibition of ICAM1 is also due to the viral miRNAs, miR-K4-3p and miR-K10a." (PMID 24039573, 2013). "The role of ICAM-1 during the latent infection stage remains to be characterized." (PMID 33602170, 2021). "The study found that lenalidomide and pomalidomide prevented MHC-I downregulation during viral lytic activation, and restored ICAM-1 and B7-2 expression on the PEL cell surface in the viral latent infection state." (PMID 38966176, 2024). "KSHV downregulates MHC-I expression during lytic infection, and expression of ICAM-1 and B7-2 (CD86) during latent infection, allowing evasion of T cell and natural killer immunity respectively." (PMID 28881567, 2017). "Furthermore, an intercellular adhesion molecule-1 (ICAM-1) and B7-2 (CD86) were downregulated in the KSHV latent infection state, enabling T cell and NK cell immune evasion, respectively." (PMID 38966176, 2024).
leukocytosis (5 papers, 2015 to 2025). "In parallel, adhesion-axis interventions informed by leukocytosis biology (e.g., ICAM-1/LFA-1, α4-integrin/VCAM-1) reduce leukocyte transmigration and BRB breakdown in vivo, supporting trafficking-based barrier protection in inflammatory retinopathies." (PMID 41394857, 2025). "Intercellular adhesion molecule-1 (ICAM-1) is directly involved in the process of vascular permeability leading to a leukocytosis in the retina." (PMID 34281192, 2021). "Oral administration of YE diminished CS-elicited induction of pro-inflammatory COX-2, iNOS, and ICAM-1 in airways and leukocytosis in BALF." (PMID 31480536, 2019). "As expected, this study showed that CS and allergic OVA enhanced the lung induction of COX-2, iNOS, and ICAM-1 responsible for lung inflammation along with marked leukocytosis in BALF." (PMID 31480536, 2019). "Previous studies have found that blocking ICAM-1 can prevent leukocytosis as well as retinal vascular leakage." (PMID 26539228, 2015). "Excess iron further promotes the expression of adhesion molecules, such as intercellular adhesion molecule 1 (ICAM1), and facilitates monocyte endothelial adhesion, both of which are critical early events in leukocytosis and microvascular dysfunction in DR." (PMID 41010490, 2025).
mastitis (5 papers, 2017 to 2024). Inflammation of breast tissue during lactation or postpartum due to an obstructed duct or infection. "The potential targets of these high-frequency CMM in treating mastitis were intercellular adhesion molecule 1 (ICAM-1), interleukin-6 (IL-6), lipopolysaccharide binding protein (LBP), and lactotransferrin." (PMID 30911319, 2019). "Moreover, using PPI network analysis, we determined that TNF, IL-6, IL-1β, CXCL8, and ICAM1 proteins were the main targets of GYS for mastitis treatment." (PMID 38630770, 2024). "The mechanism of them in treating mastitis might be that they inhibit ICAM-1 and thereby exert certain anti-inflammatory effects." (PMID 30911319, 2019). "As previously reported in other tissues, CXCL1 (KC), CXCL2 (MIP2), ICAM-1, ACKR1, Selp (P-selectin), and Itgam (Cd11b), are all most probably involved in transendothelial neutrophil trafficking in mastitis." (PMID 37032878, 2023).
myeloid leukemia (5 papers, 2009 to 2024). A clonal proliferation of myeloid cells and their precursors in the bone marrow, peripheral blood, and spleen. "ICAM-1 seems to be the predominant mechanism responsible for myeloid leukemia cell killing as a CRISPR screen in the K562 cell line identified ICAM-1 perturbation with the highest score of NK92 evasion mechanisms." (PMID 39034990, 2024). "However, bohemamine and deoxybohemamine were shown to be inhibitors of cell adhesion based on LFA-1/ICAM-1 capable of inhibiting adhesion of human pro-myelocytic leukemia HL-60 cells to Chinese hamster ovary cells transfected with human ICAM-1, at IC50 values of 24.3 and 27.2 μg/mL, respectively." (PMID 19597582, 2009). "Thus, we detected the expression of ICAM-1 on the surface of leukemic cells and confirmed that ICAM-1 was highly expressed on the both lymphocytic and myelocytic leukemia cells." (PMID 38971796, 2024).
nasal polyps (5 papers, 2010 to 2018). "The flow cytometry analysis of lymphocytes isolated from nasal polyps revealed a significant increase of IL-2 receptor and ICAM-1 molecule expression on T cells isolated from nasal polyps when compared with peripheral blood lymphocytes." (PMID 20214821, 2010). "Due to the fact that E-selectin, P-selectin, PSGL1, ICAM1, and VCAM1 are expressed by inflamed endothelial cells, we determined the expression of CD31, a specific endothelial cell marker, in nasal polyps and inferior turbinates of 7 patients." (PMID 24995349, 2014). "Additional staining showed increased expression of VCAM1 in sections of nasal polyps compared to the inferior turbinates and similar expression of ICAM1 (data not shown)." (PMID 24995349, 2014). "Expression levels of PSGL1, ICAM1, and VCAM1 did not significantly differ between nasal polyps and inferior turbinates." (PMID 24995349, 2014).
osteoporosis (5 papers, 2013 to 2024). A condition of reduced bone mass, with decreased cortical thickness and a decrease in the number and size of the trabeculae of cancellous bone (but normal chemical composition), resulting in increased fracture incidence. "In the OVX-induced osteoporosis model, we detected overexpression of ICAM-1, which was decreased in the WSP-AbM-treated group." (PMID 24348690, 2013). "The active mode of WSP-AbM in the prevention of OVX-induced osteoporosis also involves inhibiting ICAM-1 expression." (PMID 24348690, 2013). "Expression of ICAM-1 on hepatocytes correlates with the degree of osteoporosis." (PMID 24348690, 2013). "Activation of NF-κB plays an important role in the pathogenesis of osteoporosis by the upregulation of TNF-α, IL-1β, ICAM-1, iNOS, and COX-2 expressions." (PMID 24348690, 2013). "WSP-AbM reduced TNF-α, IL-1β, ICAM-1, iNOS, and COX-2 expressions and osteoporosis by the inhibition of NF-κB activation." (PMID 24348690, 2013).
pancreatic ductal adenocarcinoma (5 papers, 2017 to 2024). An infiltrating adenocarcinoma that arises from the epithelial cells of the pancreas. "Mutated Kras induces the expression of ICAM-1, which serves as a chemoattractant for macrophages and contributes to the formation of pancreatic intraepithelial neoplasms (PanINs), the most common precursor lesions for pancreatic ductal adenocarcinoma." (PMID 30383833, 2018).
peripheral arterial disease (5 papers, 2015 to 2026). A disorder of the arteries supplying the upper and lower extremity and the visceral organs. "In support of this theory, it was shown that the circulating levels of cytokines (IL-6 and TNFα), adhesion molecules (VCAM-1 and ICAM-1), and selectins in patients with peripheral arterial disease are elevated." (PMID 34447794, 2021).
promyelocytic leukemia (5 papers, 2008 to 2021). "Additionally, the expression of MMP9 by human promyelocytic leukemia HL-60 cell line has been associated with intercellular adhesion molecule-1 (ICAM-1) shedding into the cell medium, which would suggest another explanation." (PMID 24086377, 2013). "ICAM-1 is involved in cell adhesion and signaling, plays an important role in tumor progression and tumorigenesis, specifically by facilitating tumor invasion, and is associated with susceptibility to many cancers, including acute promyelocytic leukemia (APL)." (PMID 33422029, 2021). "A recent study has indicated that SNP rs5498 E469K but not rs1799969 R241G in the ICAM-1 gene is associated with the development of differentiation syndrome in actue promyelocytic leukemia." (PMID 18505543, 2008). "In addition, heparin reduced acute promyelocytic leukemia cell line NB4 adhesion to the immortalized human microvascular endothelial cell line-1 (HMEC-1), and the expression of intercellular adhesion molecule 1 (ICAM-1) and vascular cell adhesion molecule 1 (VCAM-1) on HMEC-1 cells." (PMID 32754595, 2020).
respiratory infections (5 papers, 2018 to 2025). "In addition, smokers are at increased risk of respiratory infections, and Icam1 is an adhesion target for bacterial and viral pathogens such as Haemophilus influenzae and rhinovirus." (PMID 36613693, 2022). "Additionally, NO2 increases ICAM-1 expression in epithelial cells, a major receptor for rhinoviruses and respiratory syncytial viruses, explaining its role as a risk factor for recurrent respiratory infections." (PMID 40365435, 2025). "For instance, NO2 increases Th2 cytokines and ICAM-1 (Intercellular Adhesion Molecule-1) epithelium expression, facilitating respiratory infections since ICAM-1 is a receptor for Rhinovirus and respiratory syncytial virus (RSV)." (PMID 36901776, 2023).
scleroderma (5 papers, 2008 to 2020). Scleroderma is a rare autoimmune connective tissue disorder characterized by abnormal hardening of the skin and, sometimes, other organs. "In particular, endothelial incubation with SSc-ICs modulates several molecules involved in the three cardinal scleroderma pathophysiologic processes: vascular dysfunction (ET-1 and IL-8), inflammation (ICAM-1, IL-6), and fibrosis (TGF-β1)." (PMID 33168071, 2020). "Significantly elevated levels of anti-ICAM-1 antibodies were detected in patients with diffuse (dSSc; 10/31 32%) or limited (lSSc; 14/36 39%) scleroderma." (PMID 23685129, 2013). "The presence of immunoglobulins (IgM or IgG) able to bind to immobilised recombinant human ICAM-1 was analysed in serum from 60 patients with scleroderma (n = 32 lSSc, n = 28 dSSc) and from 26 healthy controls." (PMID 23685129, 2013). "In particular, the incubation with SSc-ICs modulated several molecules involved in the three cardinal scleroderma pathophysiologic processes: vascular dysfunction (ET-1 and IL-8), inflammation (ICAM-1, IL-6, IFNs and MCP-1) and fibrosis (TGF-β1 and Pro-CollagenIα1)." (PMID 30157947, 2018). "Here, we have recapitulated those findings after purifying anti-ICAM-1 antibodies from scleroderma patients, and shown that the purified antibodies bind to the cell surface of HUVEC, and after cross-linking induce an increase in ROS generation and VCAM-1 expression." (PMID 23685129, 2013). "We have preliminary data (not shown) to demonstrate that the anti-ICAM-1 antibodies purified from scleroderma patients are able to activate MAPK pathways in HUVEC, in agreement with our previous findings with monoclonal anti-ICAM-1 antibodies." (PMID 23685129, 2013).
serous ovarian carcinoma (5 papers, 2014 to 2024). "In TCGA data, amplification/mutation of ICAM1 was identified in 12% of serous ovarian carcinoma samples, and overexpression of ICAM1 mRNA predicted reduced overall survival in SOC." (PMID 31312656, 2019). "Aim: to analyze mRNA expression of EGFL7 within the tumor microenvironment of high-grade ovarian serous carcinoma and its association with a number of intraepithelial CD4+/CD8+ lymphocytes and ICAM-1 expression." (PMID 35630004, 2022). "Data on ICAM1 expression and mutations in serous ovarian carcinoma (SOC) were obtained from the Cancer Genome Atlas (TCGA), and ICAM1 mRNA expression data in HGSOC were obtained from the Gene Expression Omnibus (GEO) database." (PMID 31312656, 2019). "Prominent among these genes were those encoding platelet derived growth factor receptor alpha (PDGFRα), vascular cell adhesion molecule (VCAM), clusterin, intercellular adhesion molecule 1 (ICAM-1), and serine/threonine phosphatase 1 (Wip1), which are overexpressed in human serous ovarian cancer." (PMID 24603706, 2014).
Sjögren’s syndrome (5 papers, 2009 to 2024). "Membrane bound ICAM-1 is over expressed in the salivary glands (SG) of Sjögren's syndrome (SS) patients and has therefore been proposed as a potential therapeutic target." (PMID 21589878, 2011). "ICAM-1 is upregulated in endothelial cells, lymphocytes, fibroblasts, and ductal epithelium of salivary glands (SG) from Sjögren's syndrome (SS) patients." (PMID 21589878, 2011).
squamous cell carcinoma (5 papers, 1999 to 2025). A carcinoma arising from squamous epithelial cells. "To validate this finding at the protein level, we performed immunohistochemical (IHC) staining of ICAM1 on a microarray of 111 human cervical tumor tissues including 107 squamous cell carcinoma and 4 adenocarcinoma." (PMID 39971940, 2025). "Pre‐treatment levels of both VCAM‐1 and ICAM‐1 were higher in patients with adenocarcinoma than in patients with squamous cells carcinoma." (PMID 34390488, 2022). "Then, to examine the possible role of SCFA on ICAM-1 expression, the oral squamous cell carcinoma cell line HSC-2 and gingival fibroblasts were cultured for 12 h with and without acetate, propionate and butyrate." (PMID 32121422, 2020). "They further showed that CD11b on the macrophages was involved in the interaction with ICAM-1 on squamous carcinoma cells and promoted their adhesion." (PMID 26231039, 2015). "When NA cells, a squamous cell carcinoma cell line, were exposed to CDDP and 5-FU for 18 h, the expression of intercellular adhesion molecule-1 (ICAM-1) was synergistically induced, whereas CDDP or 5-FU alone did not induce the expression of ICAM-1, as determined by flow cytometry." (PMID 10362102, 1999). "The synergistic effect of CDDP and 5-FU was not specific to NA cells, since ICAM-1 was synergistically induced by CDDP and 5-FU on HSC-4 cells, a squamous cell carcinoma cell line." (PMID 10362102, 1999).
thalassemia (5 papers, 2011 to 2025). An inherited blood disorder characterized by a decreased synthesis of one of the polypeptide chains that form hemoglobin. "A total of 10 records from eligible studies established the levels of ICAM-1 in both thalassemia patients and healthy individuals." (PMID 40332500, 2025). "The ICAM-1 outcome was significantly elevated in the thalassemia group compared to the healthy controls." (PMID 40332500, 2025). "This systematic review and meta-analysis identifies ICAM-1, VCAM-1, E-selectin, P-selectin, and ET-1 as biomarkers for assessing cardiovascular risk in thalassemia patients, underscoring their potential for early detection and targeted interventions in clinical practice." (PMID 40332500, 2025). "As thalassaemia MPs could induce TF, IL-6, IL-8, ICAM-1, VCAM-1 and E-selectin expression, the potential functional consequences of MPs influence on the adhesion of endothelial cells and monocytes was examined." (PMID 30158562, 2018). "Binding to ICAM1 was also lower in HbAS non-thalassemia pRBCs (1819.2, 1160.7–2625.1; P = 0.014)." (PMID 25893206, 2014). "This review highlights ICAM-1, VCAM-1, E-selectin, P-selectin, and ET-1 as key biomarkers for cardiovascular complications in thalassemia." (PMID 40332500, 2025). "Accordingly, this systematic review and meta-analysis aims to explore the levels of endothelial biomarkers, including ICAM-1, VCAM-1, E-selectin, P-selectin, vWF, EMPs, NO, NOS, ADMA, and ET-1, in both thalassemia patients and healthy individuals." (PMID 40332500, 2025). "This meta-analysis found that the expression levels of endothelial adhesion molecules, including ICAM-1, VCAM-1, E-selectin, and P-selectin, were significantly elevated in thalassemia patients compared to healthy individuals." (PMID 40332500, 2025). "The results showed significantly elevated levels of ICAM-1 (SMD 2.15, 95% CI: 1.09–3.22), VCAM-1 (SMD 2.50, 95% CI: 1.35–3.66), E-selectin (SMD 1.21, 95% CI: 0.92–1.50), P-selectin (SMD 1.62, 95% CI: 0.83–2.42), and ET-1 (SMD 1.23, 95% CI: 0.03–2.42) in thalassemia patients." (PMID 40332500, 2025).
Thrombocytopenia (5 papers, 2012 to 2025). A reduction in the number of circulating thrombocytes. "Patients with severe thrombocytopenia exhibited higher levels of ICAM-1, demonstrating that enhanced endothelial activation and weakened vascular integrity are involved in disease aggravation." (PMID 34326842, 2021). "This foreign interface may generate activation of plasma proteins, platelet aggregation, leading to thrombogenesis and consequent thrombocytopenia, involving cell adhesion molecules, such as intercellular adhesion molecule 1 (ICAM-1)." (PMID 37440588, 2023).
AIDS (4 papers, 2012 to 2024). A syndrome resulting from the acquired deficiency of cellular immunity caused by the human immunodeficiency virus (HIV). "Several studies have demonstrated that circulating levels of ICAM-1 are increased in HIV-infected and acquired immune deficiency syndrome (AIDS) persons." (PMID 22558273, 2012). "We then evaluated any associations between blood circulating EVs expressing the different immune cell surface markers (PD-L1, CD40, CD40L, B7-H3, TNF-RII, IL-6Rα, ICAM-1 or FasL) and tumor subtype of AIDS-NHL patients." (PMID 35655072, 2022).
amyloid (4 papers, 2008 to 2025). "Additionally, the elevation of ICAM-1 expression in irradiated mice raises the possibility that vascular changes might underlie radiation-induced amyloid accumulation." (PMID 23300905, 2012). "In postmortem AD brains, s-ICAM-1 aggregates localize to peri-plaque astrocytes, early and late stage amyloid senile plaques, and cerebral vessels." (PMID 32498476, 2020).
aortic atherosclerosis (4 papers, 2011 to 2025). A atherosclerosis that involves the aorta. "Reduces the area of aortic atherosclerosis.Decreases serum and aortic ROS, HO-1, NF-κB, ICAM-1 and gp91phox.Increases serum and aortic Nrf2, eNOS and p-eNOS." (PMID 41300435, 2025). "We demonstrate the efficacy of the I-domain fragment of LFA-1 (idLFA-1) complexed to modified nanocarriers to facilitate the homing of mesenchymal stem cells (MSCs) to inflamed luminal endothelial cells on which ICAM-1 is highly expressed in a murine model of aortic atherosclerosis." (PMID 40630903, 2025).